5_8S_rRNA (5.8S ribosomal RNA )
Synonyms: RNA5-8SP; LOC110467522
Gene: Ribosomal RNA gene on chromosome 20 (29,741,510 to 29,741,661, reverse strand). Ensembl gene ENSG00000283291.
Gene Ontology:
Molecular function: structural constituent of ribosome
Cellular component: ribosome
Homologues: Orthologues: zebrafish 5_8S_rRNA (86% identical), zebrafish si:dkeyp-3b12.15 (86% identical), zebrafish 5_8S_rRNA (85% identical), rat 5_8S_rRNA (84% identical), rat 5_8S_rRNA (83% identical), rat 5_8S_rRNA (82% identical), chimpanzee 5_8S_rRNA (81% identical), rat 5_8S_rRNA (81% identical), rat 5_8S_rRNA (80% identical), rat 5_8S_rRNA (79% identical), rat 5_8S_rRNA (78% identical), mouse Gm54867 (74% identical), and 1 more. Paralogues in human: 5_8S_rRNA (89% identical), 5_8S_rRNA (87% identical), RNA5-8SN1 (87% identical), RNA5-8SN2 (87% identical), RNA5-8SN3 (87% identical), RNA5-8SN4 (87% identical), RNA5-8SN5 (87% identical), 5_8S_rRNA (86% identical), 5_8S_rRNA (85% identical).